GPA33 (glycoprotein A33)
Description:
May play a role in cell-cell recognition and signaling.
Synonyms: A33
Tractability: Antibody: a drug acting on it is in phase 2 or 3 trials; its Gene Ontology location is reachable by antibodies, with high confidence; UniProt predicts a signal peptide or a membrane-spanning region.
Gene: Protein-coding gene on chromosome 1 (167,048,289 to 167,166,479, reverse strand). Ensembl gene ENSG00000143167.
Subcellular location: Membrane
Gene Ontology:
Molecular function: protein binding; signaling receptor activity
Cellular component: extracellular exosome; plasma membrane; membrane
Genetic constraint (gnomAD): Loss-of-function variants: 25 observed, 36.49 expected, observed/expected ratio (o/e) 0.69, 90% interval 0.5 to 0.96. The upper end of that interval is the gene's LOEUF score, 0.96, which puts it in group 4 of 6, group 1 being the genes least tolerant of losing a copy. Missense variants: 427 observed, 428.54 expected, observed/expected ratio (o/e) 1, 90% interval 0.92 to 1.08. Synonymous variants: 175 observed, 171.85 expected, observed/expected ratio (o/e) 1.02, 90% interval 0.9 to 1.15.
Homologues: Orthologues: chimpanzee GPA33 (94% identical), macaque GPA33 (88% identical), dog GPA33 (72% identical), pig GPA33 (70% identical), rabbit GPA33 (68% identical), rat Gpa33 (65% identical), mouse Gpa33 (64% identical), guinea pig GPA33 (63% identical), tropical clawed frog gpa33 (40% identical), zebrafish gpa33b (19% identical). Paralogues in human: IGSF11 (27% identical), CLMP (25% identical), CXADR (25% identical), VSIG1 (24% identical), VSIG8 (22% identical), ESAM (22% identical), VSIG2 (21% identical), F11R (18% identical), JAM2 (18% identical), JAM3 (18% identical), MXRA8 (16% identical), VSTM2B (14% identical), and 2 more.
Diseases named in the same sentence as GPA33 in open-access papers:
GPA33 is named in the same sentence as 36 diseases in open-access papers, as found by Europe PMC text mining. Sharing a sentence is not in itself a finding about the gene and the disease. The quoted sentences say what the papers report.
colorectal cancer (29 papers, 1996 to 2026). A primary or metastatic malignant neoplasm that affects the colon or rectum. "GPA33 is highly expressed in most human colorectal cancers and has been verified as a diagnostic and therapeutic target." (PMID 26090413, 2015). "This indicates that GPA33 may be a diagnostic marker and potential therapeutic target for GC and colorectal cancer." (PMID 35923703, 2022). "Clinically, GPA33 expression has been observed in over 95% of colorectal cancers (CRCs) and associated metastases, an observation that has underpinned an ongoing and concerted effort to use radionuclide-bound murine and humanised (huA33 mAb) monoclonal antibodies to target GPA33-expressing tumours." (PMID 26035389, 2015). "In vivo, using a DOTA-PRIT system targeting the GPA33 antigen in a human colorectal cancer mouse model, [68Ga]Ga-NODAGA-Pr demonstrated efficient tumor uptake and high-contrast PET imaging." (PMID 42151769, 2026). "Our detailed phenotypic characterization of GPA33 expressing tumors revealed a heterogeneous expression of GPA33 within colorectal cancers." (PMID 39472498, 2025). "The most sensitive markers for GI origin were GPA33 (positive in 98%, 60%, and 100% of pulmonary metastases from colorectal cancer, pancreatic cancer, and other GI adenocarcinomas, respectively), CDX2 (99/40/100%), and CDH17 (99/0/100%)." (PMID 37349623, 2024). "GPA33 has previously been demonstrated to be highly expressed in gastric and colorectal cancer and human anti-GPA33 antibodies are being evaluated as immuno-oncological treatments." (PMID 38604503, 2024). "Early phase clinical trials of monoclonal anti-GPA33 showed good safety and tolerability, while other clinical trials investigating novel anti-GPA33 antibodies in colorectal cancer are ongoing (NCT02248805)." (PMID 38604503, 2024). "Thereby, GPA33 constitutes an ideal antigen for the development of colorectal cancer-directed immunotoxins and thus was employed as the target of different immunotoxins already designed by our group." (PMID 36831456, 2023). "Recently, it was reported that GPA33-targeted NIR-PIT induced cell-specific cytotoxicity against GPA33-positive colorectal cancer cells in xenograft models." (PMID 35453596, 2022). "The role of GNAS R201C and R201H in CRC tumourigenesis under the control of the Gpa33-antigen promoter is almost exclusively expressed in colorectal cancer." (PMID 36428574, 2022). "The role of GNAS gene codons R201C and R201H in CRC tumourigenesis under the control of the Gpa33-antigen promoter is almost exclusively expressed in colorectal cancer." (PMID 36428574, 2022). "Alternatively, bridging molecules can be used to create new EV-tumor interactions: glycoprotein A33 is specifically expressed in the gut epithelium and colorectal carcinomas (CRC)." (PMID 32668783, 2020). "In fact, we began by preparing A33scFv and evaluating its potential as an imaging agent for GPA33-positive colorectal cancer." (PMID 26090413, 2015). "HuA33 is a humanized monoclonal antibody (mAb) directed against GPA33 and has been studied in phase I trials in patients with colorectal cancer." (PMID 24995151, 2014). "One of the most promising targets in colorectal cancer is the A33 antigen (hereafter referred to as GPA33): a transmembrane glycoprotein of the immunoglobulin superfamily with a molecular weight of 43 kDa." (PMID 24995151, 2014). "GPA33 is a specific marker of colorectal cancer cells expressed on 95% of colorectal cancers." (PMID 41596412, 2026). "For this purpose, in this work we have designed a novel trimeric immunotoxin (IMTXTriA33αS) against colorectal cancer, combining the scFv against GPA33 as a targeting domain and the fungal ribotoxin α-sarcin (αS) as the toxic fragment, linked by a trimerization domain (TIEXVIII)." (PMID 41596412, 2026). "GPA33 is a promising surface antigen for targeted therapy in colorectal cancer (CRC)." (PMID 39472498, 2025).
colorectal cancer (continued). "Glycoprotein A33 antigen (GPA33) could be another target of NIR-PIT in colorectal cancer because it is highly expressed in over 95% of human colorectal cancers, more than 60% of gastric cancers, and 50% of pancreatic cancers." (PMID 34064074, 2021). "The A33scFv-Fc specifically binds GPA33-positive colorectal cancer cells and tumor tissues." (PMID 26090413, 2015). "GPA33, a 43 kDa membrane glycoprotein, is highly expressed in over 95% of human colorectal cancers." (PMID 26090413, 2015). "Our data further support that CDH17, GPA33, and SATB2 in addition to CDX2 are all very sensitive markers for colorectal cancer metastases, and slightly more sensitive than CK20." (PMID 37349623, 2024). "Thus, GPA33-targeted NIR-PIT could be a promising cancer therapy for colorectal cancer patients." (PMID 35453596, 2022). "Both constructs were also able to specifically bind to GPA33 expressed on the surface of the membrane and be internalized into SW1222 colorectal cancer cells, indicating that the targeting domain was fully functional." (PMID 31614771, 2019). "GPA33 is a well-known colorectal cancer marker that is overexpressed in 95% of colorectal cancer but absent from other healthy tissues." (PMID 36831456, 2023). "Although its specific function is currently unclear, studies have found that GPA33 is expressed in more than 95% of colorectal cancers and about 70% of GCs, but not in normal epithelial cells." (PMID 35923703, 2022). "GPA33 was discovered as a novel membrane protein and is highly upregulated in more than 95% of colorectal cancers but is not expressed in adjacent normal cells." (PMID 35453596, 2022). "Furthermore, we analyzed GPA33 protein expression in a case-control collection of 32 matched pairs of metastatic and non-metastatic colorectal cancers." (PMID 39472498, 2025).
colon carcinoma (21 papers, 2012 to 2025). "On the contrary, we did not observe effects on tumor cell growth for GPA33-negative SW480 colon cancer cells challenged with GPA33-CAR T cells." (PMID 39472498, 2025). "Next, we assessed differences in signaling pathway activities of colon cancer cell subpopulations with differential GPA33 mRNA expression, using single-cell transcriptome sequencing data of 12 samples of freshly resected colon cancers." (PMID 39472498, 2025). "To determine if GPA33-CAR T cells target GPA33-positive colon cancer in vivo, we used T84 cell line derived colon cancer xenografts." (PMID 39472498, 2025). "Our results provide further evidence of the potential of GPA33 antigen as a specific tumor-marker for colon cancer becoming a good alternative to those actually used in therapy." (PMID 25883890, 2015). "Of these antibodies, A33 (a murine monoclonal antibody against GPA33) and huA33 (the humanized A33) have been widely used as imaging tools for mice with human colon cancer xenografts and for colon cancer patients." (PMID 26090413, 2015). "IMTXA33αS shows a highly specific and effective cytotoxicity against colon cancer target cells (SW1222 or LIM1215) overexpressing the GPA33 antigen, with IC50 (protein concentration inhibiting 50% of protein synthesis) values of 30 and 70 nM, respectively." (PMID 25883890, 2015). "Here we report the in vivo antitumor effectiveness of this immunotoxin on nude mice bearing GPA33-positive human colon cancer xenografts." (PMID 25883890, 2015). "In this work we move one step further and demonstrate the potential of IMTXA33αS for in vivo applications, using SW1222-induced xenografts, as a model of GPA33-positive colon cancer." (PMID 25883890, 2015). "Due to its features, GPA33 represents an ideal target for immunotoxins aimed against colon cancer cells." (PMID 25883890, 2015). "Previous studies have demonstrated a high and uniform expression of GPA33 in colon cancers and throughout the normal intestinal mucosa." (PMID 24995151, 2014). "This suggests that inhibition of WNT in human patients to enhance GPA33 expression in colon cancer may be feasible for induction of this therapeutic target." (PMID 39472498, 2025). "However, we found a significant anti-tumor response after intratumoral GPA33-CAR T cell injection into colon cancer xenografts." (PMID 39472498, 2025). "For example, various types of microRNAs and long non-coding RNAs in blood or stool samples have been significantly correlated with colon cancer, and some tissue biomarkers (including caudal type homeobox 2, special AT-rich sequence-binding protein 2, and glycoprotein A33) have been identified." (PMID 38366023, 2024). "Furthermore, GPA33 is overexpressed in >95% of colon cancers and >60% of gastric cancers and is identified as a Barrett metaplasia marker." (PMID 33671266, 2021). "In addition, the GPA33 glycoprotein which is similar to VSIG1 is markedly increased in most colon cancers and has been used as a target for therapeutics." (PMID 24533081, 2014). "Strikingly, however, Gpa33−/− mice are more susceptible than WT to DSS-induced loss of intestinal barrier function and severe colitis and, when DSS treatment is coupled with prior administration of the mutagen AOM, they develop significantly more and larger colon tumours." (PMID 26035389, 2015). "Importantly, when we analyzed six individual pairs of primary colon cancers and corresponding liver metastases, expression and distribution patterns of GPA33-positive and -negative tumor cells with loss of GPA33 at the infiltrative tumor edge were preserved between primary tumors and metastases." (PMID 39472498, 2025). "In contrast, colon cancer organoids did not sufficiently reproduce GPA33 heterogeneity and thus were excluded as models for further experiments." (PMID 39472498, 2025).
colon carcinoma (continued). "GPA33 gene is expressed primarily in the normal intestine and in >95% of colon tumors but not by other normal tissues, and is a therapeutic target in colon cancer immunotherapy." (PMID 26536629, 2015). "Here, we showed that expression of the same version of β-catenin, albeit as a homozygous knock-in transgene and under the control of the gpA33 locus, resulted primarily in colonic tumors without detrimental effects in other organs." (PMID 26398937, 2015).
colitis (5 papers, 2015 to 2022). Inflammation of the colon. "Protein GPA33 is a marker of Treg cells, and GPA33-deficient mice would increase the rate of colitis." (PMID 35893911, 2022). "Consistently, GPA33-deficient mice showed higher mortality than wild-type mice following colitis induction." (PMID 33672304, 2021). "Gpa33−/− mice exhibited a more rapid onset of colitis compared to WT mice, shown by increased weight loss, and histological damage." (PMID 26035389, 2015). "To investigate the effect of GPA33 deficiency on susceptibility to colitis induction, we treated Gpa33−/− mice with 2% DSS." (PMID 26035389, 2015). "At the 192 h time point, both genotypes exhibited similar colitis severity, suggesting that Gpa33 deficiency mostly affects colitis onset." (PMID 26035389, 2015). "Studies using the 2,4,6-trinitrobenzene sulfonic acid/ethanol-induced colitis model confirmed the role of GPA33." (PMID 33672304, 2021). "Gpa33–/– mice exhibited hypersensitivity to food antigens and a markedly increased severity of colitis upon exposure to DSS." (PMID 26035389, 2015). "To test a potential requirement for GPA33 in intestinal barrier function, we generated Gpa33−/− mice and subjected them to experimental regimens designed to produce food hypersensitivity, colitis and CAC." (PMID 26035389, 2015). "Gpa33−/− mice also exhibited rapid onset and reduced resolution of DSS-induced colitis, and a striking increase in the number of colitis-associated tumours produced by treatment with the colon-specific mutagen azoxymethane (AOM) followed by two cycles of DSS." (PMID 26035389, 2015). "Maximal colitis in Gpa33−/− mice was observed at 104 h, whereas the colitis score significantly increased between 104 h and 192 h (P<0.01) in WT mice, demonstrating accelerated onset and progression of DSS-induced colitis in Gpa33-deficient animals." (PMID 26035389, 2015). "Gpa33−/− mice also exhibited increased susceptibility to chronic colitis as shown by more exaggerated weight loss following each cycle of DSS and impaired crypt regeneration and resolution of colonic inflammation compared to WT." (PMID 26035389, 2015). "Using a harsher regime of DSS treatment (2% DSS in drinking water for 104 h), Gpa33−/− mice exhibited a rapid onset of acute colitis, indicative of luminal antigen penetration into the LP, most likely caused by TJ impairment and enhanced paracellular permeability." (PMID 26035389, 2015). "To test whether the rapid induction and impaired resolution of colitis in Gpa33−/− mice leads to increased development of CAC, we employed the azoxymethane (AOM)/DSS model." (PMID 26035389, 2015). "Therefore, the increased levels of PBLD, FAM3D, KRT8, SULT2B1, GPA33, DEPTOR, and decreased expression of ACSL4, IFITM1 and HSD11B1 caused by mEVs has been demonstrated to attenuate colitis, implying that consumption of mEVs has the potential to improve intestinal health." (PMID 35893911, 2022). "GPA33 knockout mice show impaired epithelial barrier function, with quick onset and delayed resolution of DSS-induced colitis." (PMID 33672304, 2021). "Intestinal epithelial cell lineage differentiation and proliferation were found to be normal in Gpa33−/− mice and, apart from an extremely mild, progressive colitis with age, which is indistinguishable from that seen in WT, Gpa33−/− mice did not exhibit steady-state colitis." (PMID 26035389, 2015). "Gpa33−/− mice on a pure C57BL/6 background are healthy and do not develop spontaneous colitis or any other gastrointestinal pathology up to 1 year of age." (PMID 26035389, 2015).
metastatic colorectal cancer (5 papers, 2014 to 2023). "Previous radioimmunotherapy studies using iodinated murine A33 mAb have shown the therapeutic potential of the GPA33 antibody system in patients with metastatic colorectal cancer." (PMID 24995151, 2014). "In this sense, the glycoprotein A33 (GPA33) is an integral membrane protein that is overexpressed in 95% of primary and metastatic colorectal cancer and is almost absent in healthy tissues." (PMID 36831456, 2023).
gastric cancer (3 papers, 2021 to 2024). A primary or metastatic malignant neoplasm involving the stomach. "Glycoprotein A33 (GPA33) is a cell surface glycoprotein that has been identified as expressed in intestinal tissues and colorectal and gastric cancer and has a putative role in cell adhesion." (PMID 38604503, 2024).
inflammatory bowel disease (2 papers, 2015 to 2023). A spectrum of small and large bowel inflammatory diseases of unknown etiology. "ANCA-negative EGPA may instead have a mucosal/barrier dysfunction origin supported by the association with barrier protein GPA33 and shared genetic architecture with inflammatory bowel diseases." (PMID 36719484, 2023). "Highlighted Article: We show that GPA33, an intestine-specific cell surface protein, plays a role in the maintenance of intestinal barrier function and the prevention of intestinal pathologies such as food hypersensitivity, inflammatory bowel disease and colitis-associated cancer." (PMID 26035389, 2015).
asthma (1 paper, 2023). "In turn, ANCA-negative EGPA has a mucosal barrier origin and is associated with variants of the glycoprotein A33 (GPA33) and IL-5/interferon regulatory factor 1 (IRF1) (genotype sharing with asthma)." (PMID 37215720, 2023).
Chronic colitis (1 paper, 2015). A chronic inflammatory disease of the large intestine (colon, cecum and rectum). "When exposed to repeated DSS cycles to induce chronic colitis akin to the flares of inflammation in IBD, Gpa33−/− mice were less able to resolve multiple bursts of epithelial damage and inflammation than WT controls." (PMID 26035389, 2015).
Crohn disease (1 paper, 2015). A gastrointestinal disorder characterized by chronic inflammation involving all layers of the intestinal wall, noncaseating granulomas affecting the intestinal wall and regional lymph nodes, and transmural fibrosis. "In individuals with either Crohn's disease (CD) or ulcerative colitis (UC), mean GPA33 expression was reduced in inflamed bowel compared to uninflamed and normal control tissue, respectively." (PMID 26035389, 2015).
cyst (1 paper, 2015). A sac-like closed membranous structure that may be empty or contain fluid or amorphous material. "Furthermore, treatment with the highest dose of immunotoxin resulted in a residual tumor mass, lacking the GPA33 antigen and with a cyst-like appearance." (PMID 25883890, 2015).
gynecological cancers (1 paper, 2024). "SATB2 was infrequently positive in gynecological cancers (12%; 2/17) and kidney cancers (10%; 4/42), while GPA33-positivity was rare." (PMID 37349623, 2024).
intestinal tumor (1 paper, 2015). "We have generated a new gpA33ΔN-Bcat knock-in mouse model to study intestinal tumor susceptibility by inserting the 1-131 amino-terminal truncation mutant of β-catenin into the 3′ UTR of the endogenous gpA33 antigen locus." (PMID 26398937, 2015).
lung adenocarcinoma (1 paper, 2024). A carcinoma that arises from the lung and is characterized by the presence of malignant glandular epithelial cells. "In comparison, SATB2 and CK20 showed higher specificity, with expression in 5% and 10% of mucinous primary lung adenocarcinomas and both in 0% of TTF-1-negative non-mucinous primary lung adenocarcinomas (25–50% and 5–16%, respectively, for GPA33/CDX2/CDH17)." (PMID 37349623, 2024).